ABCB1 (ATP binding cassette subfamily B member 1)
Diseases named in the same sentence as ABCB1 in open-access papers (continued):
Sharing a sentence is not in itself a finding about the gene and the disease.
ovarian carcinoma (continued). "Therefore, it is meaningful to analyze the association between ABCB1 and prognosis in different ovarian cancer subtypes separately." (PMID 27812204, 2016). "For ABCB1 gene polymorphisms, although rs2235023, rs13237132, rs12334183, rs10264990, and rs4148732 were previously reported to be associated with ovarian cancer outcome, evidences from a study of more than 10000 cases suggested these candidate polymorphisms were not correlated with EOC prognosis." (PMID 27812204, 2016). "Indeed, several studies, including a meta-analysis of 38 retrospective studies assessing 8067 epithelial ovarian cancer cases, demonstrated that ABCB1 over-expression was a significant risk factor associated with unfavorable overall and progression-free survival." (PMID 34830797, 2021). "Independent studies have confirmed high expression of ABCB1 in paclitaxel-resistant ovarian cancer cells and ABCG2 in topotecan-resistant cells." (PMID 41303640, 2025). "At the same time, ABCB1 inhibitors (e.g., verapamil and elacridar) can reverse ABCB1-mediated resistance in ovarian cancer cells treated with olaparib." (PMID 41357999, 2025). "NOB can significantly increase the chemosensitivity of ABCB1-overexpressed ovarian cancer cells and paclitaxel-resistant lung cancer cells to paclitaxel, doxorubicin, docetaxel, and daunorubicin and reverse MDR." (PMID 41425709, 2025). "Several studies indicate that overexpression of ABCB1 (also named MDR1) correlates with drug resistance in ovarian cancer." (PMID 40507922, 2025). "Following 24-h co-incubation of ovarian cancer cells with exosomes (exoctrl or exotLyP-1) loaded with cholesterol-modified ABCB1 siRNA, qRT-PCR detected significant gene silencing." (PMID 41306963, 2025). "For instance, erastin can inhibit the progression of triple-negative breast cancer and reverse ABCB1-mediated docetaxel resistance in ovarian cancer." (PMID 40764425, 2025). "In fact, it has been proved that an increased expression of ABCB1 is involved in the occurrence of MDR in ovarian cancers treated with taxane drugs (e.g., Paclitaxel)." (PMID 38203758, 2024). "In ABCB1 overexpressed ovarian cancer cells, erastin co-delivery with docetaxel significantly reduced cell viability, promoted apoptosis, and induced cell cycle arrest at G2/M." (PMID 38469234, 2024). "Up-regulation of ABCB1 is the reason for the docetaxel resistance in patient with ovarian cancer with poor survival." (PMID 38469234, 2024). "Inhibition of P-glycoprotein (ABCB1) by erastin has also been previously reported in human ovarian cancer cells." (PMID 38730685, 2024). "Another found that the ABCB1 inhibitors verapamil and elacridar reverse resistance in ovarian cancer cell lines overexpressing ABCB1." (PMID 38236558, 2024). "Whole-genome microarray analysis revealed that ABCB1 was the only drug transporter with increased expression in resistant ovarian cancer cells, while the expression of several other ABC transporters was significantly decreased." (PMID 38539161, 2024). "Aberrant expression of the Hedgehog signaling pathway transcription factor Gli1 has been found to be involved in the modulation of ABCB1 in ovarian cancer." (PMID 38228910, 2024). "A 2019 report on ovarian cancer introduced Erastin, a ferroptosis inducer, which countered docetaxel resistance mediated by ABCB1 (a pathway promoting drug efflux from cells) and promoted ferroptosis in ovarian cancer cells." (PMID 39061859, 2024). "Expression of ABCB1 is elevated in various cancers, including acute myeloid leukemia, ovarian carcinoma, non-small cell lung cancer, breast and PCa." (PMID 39090086, 2024). "Aberrant Notch pathway can cause drug resistance in ovarian cancer cells, whereas Notch knockdown can increase platinum sensitivity through downregulation of ABCC1 and ABCB1." (PMID 38539161, 2024). "The majority of research on the Gli-mediated transcription of ABCB1 has been done in models of ovarian cancer." (PMID 37954979, 2023).
ovarian carcinoma (continued). "CD109-overexpressed A2780 cells showed an increase in ABCB1 and ABCG2 protein expression levels, which are associated with drug resistance and the poor prognosis of ovarian cancer." (PMID 37373457, 2023). "Mutations that result in overexpression of ABCB1 increase transcription of the drug efflux pump MDR1 (P-glycoprotein), and were found in tissue samples from PARPi-treated breast and ovarian cancers." (PMID 37430137, 2023). "It has been reported that erastin overcomes ABCB1-mediated docetaxel resistance in ovarian cancer, offering an effective strategy for chemo-resistant patients." (PMID 37296105, 2023). "Using qHTCS, this work found a group of doxorubicin potentiators in an ABCB1-mediated MDR ovarian cancer cell line." (PMID 36439493, 2022). "Overexpression of ATP binding cassette subfamily B member 1 (ABCB1) is a well-known molecular mechanism responsible for multidrug resistance (MDR) in malignancies such as ovarian cancer." (PMID 36439493, 2022). "Research on patients with ovarian cancer has found that high levels of ABCB1 expression are inversely related to chemotherapy response and progression-free survival." (PMID 36439493, 2022). "For example, using the gene editing tool CRISPR/Cas9 to “knock down” ABCB1 can enhance doxorubicin sensitivity in doxorubicin-resistant A2780/ADR human ovarian cancer cells." (PMID 36551731, 2022). "To explore potential novel therapies for ABCB1-mediated MDR ovarian cancer cases in the clinic, we conducted a qHTCS against an ABCB1-overexpressing MDR ovarian cancer cell line, A2780-ADR." (PMID 36439493, 2022). "An increase in the copy number of ABCB1 was a result of the amplification of specific regions on chromosome 7q21 in ovarian cancer, which was a consistent finding in several studies." (PMID 36253861, 2022). "A phase II clinical trial of cediranib with olaparib in the patients with progression of ovarian cancer after PARPi treatment showed that ABCB1 upregulation is clinically important, and a poor outcome is observed if ABCB1 expression is increased." (PMID 36559065, 2022). "Mechanistically, UCA1 can sponge miR-129 and increase the expression of ABCB1, contributing to paclitaxel resistance in ovarian cancer." (PMID 36105363, 2022). "ABCB1 is a 170 kDa unidirectional membrane-bound glycoprotein known to reduce the concentration of platinum- and taxane-based chemotherapeutics in ovarian cancer cells." (PMID 36551731, 2022). "Unfortunately, ABCB1-mediated resistance is the reason for the major failure of ovarian cancer treatment with paclitaxel, doxorubicin, and PARPi, such as olaparib or rucaparib." (PMID 36559065, 2022). "Previous studies have shown that knockdown of the ABCB1 gene can re-sensitize and increase the intracellular accumulation of chemotherapeutics in drug-resistant ovarian cancer cells, making it a suitable target for treatment." (PMID 36551731, 2022). "In ovarian cancer, ferroptosis inducer erastin was proved to dominantly elevate the intracellular ABCB1 levels by restricting its drug-efflux activity, thus reversing ABCB1-mediated docetaxel resistance." (PMID 39282153, 2022). "In this study, we reported that the CAMK2/CREB pathway, particularly CAMK2D, is a promising target for reversing ABCB1-mediated drug resistance in ovarian cancer." (PMID 36439493, 2022). "Together, inhibition of the Ca2+ mediated CAMK2D/CREB1 pathway appears to be a promising therapeutic target for doxorubicin resensitization in ABCB1-mediated MDR ovarian cancer." (PMID 36439493, 2022). "Targeted regulation of ABCB1 expression can sensitize ovarian cancer cells to paclitaxel and cisplatin, providing an effective treatment option for patients with chemoresistant ovarian cancer." (PMID 35719392, 2022). "In accordance with our findings, Zhou and colleagues found that OE of the drug efflux transporter ABCB1 in ovarian cancer cells led to DTX and erastin resistance." (PMID 35402284, 2022).
ovarian carcinoma (continued). "Genes significantly downregulated by ALDH1A1 inhibition included stem cell markers (CD44, FZD7, and SOX9) and genes involved in chemoresistance (ABCB1 and NFκB) in ovarian cancer." (PMID 35884498, 2022). "Recent studies indicate that expression of ABCB1 is a useful predictor of paclitaxel resistant for patients with ovarian cancer." (PMID 34504843, 2021). "Growing evidence showed that the increased risk of adverse events during treatment in some types of cancers, including acute myeloid leukemia (AML), ovarian cancer, osteosarcomas, and melanoma, is closely related to the high expression of ABCB1." (PMID 34572328, 2021). "We show that ABCB1-overexpressing ovarian cancers are particularly sensitive to paclitaxel combined with lapatinib in the laboratory setting and that ABCB1 overexpression is common and predictive of paclitaxel sensitivity in patient-derived ovarian organoids." (PMID 34347777, 2021). "The current study demonstrates that ABCB1 upregulation is the major driver of paclitaxel resistance in two different human ovarian cancer cell line models of acquired resistance." (PMID 34347777, 2021). "MET overexpression was shown to trigger an increase of BRCP/ABCG2 and ABCB1/MDR1 expression in doxorubicin-resistant (DR) ovarian carcinoma cells and in cisplatin-resistant NSCLC cell lines respectively." (PMID 33526881, 2021). "We report that among a panel of tested TKIs, lapatinib, and poziotinib demonstrated the strongest synergy in combination with paclitaxel in ABCB1-overexpressing human ovarian cancer cells." (PMID 34347777, 2021). "Recent in vitro studies have shown lapatinib can partially reverse multidrug resistance in ABCB1-overexpressing ovarian cancer cells, findings further supported through in vivo mouse models." (PMID 34347777, 2021). "We tested a panel of tyrosine kinase inhibitors for the ability to sensitize resistant ABCB1-overexpressing ovarian cancer cell lines to paclitaxel." (PMID 34347777, 2021). "We show that for ovarian cancer cells overexpressing ABCB1, the combination treatment of lapatinib and paclitaxel has synergistic effects, sensitizing otherwise resistant cells to paclitaxel." (PMID 34347777, 2021). "In fact, in the treatment of ovarian cancer with paclitaxel, ABCB1 overexpression was reported to correlate inversely with the probability of survival." (PMID 34572328, 2021). "Re-evaluation of this combination therapy is warranted, with a new focus on ABCB1-overexpressing ovarian cancers." (PMID 34347777, 2021). "In conclusion, lapatinib and poziotinib combined with paclitaxel synergizes to inhibit the proliferation of ABCB1-overexpressing ovarian cancer cells in vitro." (PMID 34347777, 2021). "We observe higher paclitaxel IC50 (i.e., the concentration required to inhibit proliferation in 50% of cells) in immortalized human ovarian cancer cell lines and patient-derived organoids with elevated ABCB1 expression." (PMID 34347777, 2021). "We performed targeted sequencing of a 500 kb region of chromosome 7 that contained both ABCB1 and SLC25A40, which is the most common translocation partner for ABCB1 in chemotherapy-treated breast and ovarian cancer patients." (PMID 33167906, 2020). "In our study, we focused on the changes in genes connected with the MDR phenotype of the ovarian carcinoma cell line, specifically on over-expression of the ABCB1 gene." (PMID 32466263, 2020). "We found that the ABCB1-overexpressing human KB-V-1 epidermal cancer cells and the ABCB1-overexpressing human NCI-ADR-RES ovarian cancer cells are equally sensitive to sitravatinib as their drug-sensitive parental KB-3-1 and OVCAR-8 cancer cells, respectively." (PMID 31941029, 2020). "Cross-resistant to topotecan has been observed in ABCB1-overexpressing human ovarian cancer cell lines." (PMID 33425914, 2020). "Convergent evolution of ABCB1 fusion is therefore frequent in chemotherapy resistant recurrent ovarian cancer." (PMID 30894541, 2019).
ovarian carcinoma (continued). "In our study, we verified a decrease in the IC50 value of docetaxel in the presence of erastin in the ABCB1-overexpressing ovarian cancer cells." (PMID 31921655, 2019). "Erastin dose-dependently decreased the IC50 values of docetaxel in A2780/Taxol cells, while there was nearly no change in A2780 cells, indicating that erastin can enhance the sensitivity of docetaxel only in the ABCB1-overexpressing ovarian cancer cells." (PMID 31921655, 2019). "High expression of the ATP-dependent detox protein ABCB1 is frequently found in chemoresistant ovarian cancer cells and recurrent ovarian cancer patients’ samples, and has been correlated with poor prognosis." (PMID 30820473, 2019). "Upregulation of ABCB1 accounts for the recurrence of resistance to docetaxel therapy in ovarian cancer with poor survival." (PMID 31921655, 2019). "In this study, we revealed that erastin can overcome docetaxel resistance and present as a magical molecule to augment docetaxel efficacy in ovarian cancer by inhibition of ABCB1." (PMID 31921655, 2019). "There was nearly no alteration in A2780 cells, suggesting that erastin can enhance docetaxel-induced apoptosis in the ABCB1-overexpressing ovarian cancer cells." (PMID 31921655, 2019). "In another study published by the same group, they presented consistent results in a primary culture of ovarian cancer cells and concluded that ABCB1 plays a critical role in paclitaxel resistance." (PMID 30986993, 2019). "Among nine of the 11 multidrug-resistant ovarian cancer cell line variants, the drug-resistant gene MDR1 (ABCB1) is co-expressed with multiple genes located in 7q21, including CROT and CDK6." (PMID 31295943, 2019). "We confirmed that the co-delivery of erastin with docetaxel significantly decreased cell viability, promoted cell apoptosis, and induced cell cycle arrest at G2/M in ovarian cancer cells with ABCB1 overexpression." (PMID 31921655, 2019). "Conversely, a decreased expression of miR-451 is correlated with higher expression of ABCB1 in other drug resistant cells, more precisely in a human ovarian cancer cell line and a human cervix carcinoma cell line." (PMID 35582590, 2019). "Upregulated ABCB1 has been confirmed as the primary protein resulting in MDR in ovarian cancer treated with paclitaxel and related taxane drugs." (PMID 31921655, 2019). "Ovarian cancers often recur and tumors acquire resistance to chemotherapy due to overexpression of the ATP-dependent efflux pump, multidrug resistance protein 1 (MDR1/P-glycoprotein/ABCB1)." (PMID 29599904, 2018). "In ovarian cancer, oHA disrupted the localization of ABCB1 with CD44 and inhibited drug efflux function." (PMID 30513961, 2018). "The human ABCB1 gene, which encodes the multidrug resistance (MDR) transporter P-glycoprotein (P-gp), is expressed in the minority of ovarian cancers at diagnosis, but has been shown to be an adverse prognostic factor in some though not all studies." (PMID 28399108, 2017). "A recent study showed that the topotecan-resistant- and doxorubicin-resistant human ovary carcinoma cell line show ABCB1 expression in both nuclear and plasma membranes, but tunicamycin-treated cells show ABCB1 mainly in the cytoplasm." (PMID 27446804, 2016). "Chemotherapy resistance is reported to correlate with up-regulation of anti-tumor agent transporter ABCB1 (p-gp) in epithelial ovarian cancer (EOC), but the results remain controversial." (PMID 27812204, 2016). "In both, the cervix cancer cell line KB-3-1 and the ovarian carcinoma cell line A2780, the ABCB1 promoter was found to be highly methylated, whereas the ABCG2 promoter was unmethylated." (PMID 27689338, 2016). "Characteristics of studies that identify ABCB1 protein (p-gp) expression in epithelial ovarian cancer." (PMID 27812204, 2016). "Functional experiments revealed that up-regulated ABCB1 expression impaired the sensitivity to cisplatin, paclitaxel, docetaxel and doxorubicin in ovarian cancer cell lines." (PMID 27812204, 2016).
ovarian carcinoma (continued). "The expression levels of ABCB1 in four kinds of ovarian cancer cells (A2780T, A2780, SKOV3-DDP and SKOV3) were knocked down by ABCB1-specific siRNA." (PMID 26317651, 2015). "ABCB1-mediated multidrug resistance (MDR) remains a major obstacle to successful chemotherapy in ovarian cancer." (PMID 26317651, 2015). "In conclusion, this study clearly demonstrates that afatinib is a potential and superior reversal drug for ABCB1-mediated MDR in human ovarian cancer." (PMID 26317651, 2015). "Since the discovery of the first ABC family member, ABCB1, in multidrug resistant ovarian cancer cells in 1976, research to identify drug transporters contributing to cancer drug resistance has been underway." (PMID 26431273, 2015). "In ovarian carcinoma cells, antisense oligomers directed against PKCα and PKCβ reversed ABCB1-mediated drug resistance." (PMID 25749379, 2015). "ABCB1 is highly expressed in human ovarian cancer and its overexpression is correlated inversely with a benign response to chemotherapy and good clinical prognosis." (PMID 26317651, 2015). "Since ABCB1 has been shown to represent an important factor for multiple drug resistance, the finding that the FKBP5/AR/ABCB1 axis plays a role in txr in ovarian cancer cells supports the usefulness of our strategy." (PMID 25460502, 2014). "We here show for the first time equivalence of ABCG2- and ABCB1-expressing ovarian cancer SP cells regarding stem cell properties such as clonogenicity, tumorigenicity, and asymmetric division." (PMID 25216521, 2014). "ABCB1 plays a critical role in drug fluxes and chemoresistance in many malignancies, including ovarian cancer." (PMID 24124770, 2013). "Our previous studies have demonstrated that the ovarian cancer cell lines of SKOV-3 and A2780 expressed transporters of ABCG2 and ABCB1 that were closely associated with the drug resistance." (PMID 23368632, 2013). "Reversal of MDR in ovarian cancer cell lines is possible with siRNA knockout of ABCB1 (MDR1) and ABCB4 (MDR3) genes, combination drug treatments, chitosan/pshRNA plasmid nanoparticle targeting of MDR1 genes, and perturbation of P-glycoprotein N-glycosylation." (PMID 22481932, 2012). "In ovarian cancer cells, the ABCB1 (MDR1) gene encodes P-glycoprotein, which targets to the luminal surface and actively effluxes a wide array of anticancer drugs, including carboplatin and paclitaxel." (PMID 22481932, 2012). "In case of the ovarian carcinoma cell lines OVCAR-5, OVCAR-4 and NCI/ADR-RES, the methylation status of CGIs associated with the genes ABCB1, BRCA1, CDH1, DNAJC15, and SULF2 was connected to the expression of the genes." (PMID 20544021, 2010). "A number of reports have focused on multidrug resistance in ovarian carcinoma, and specifically on the drug efflux pump P-glycoprotein, whose gene ABCB1 is situated in 7q21.12." (PMID 19835627, 2009). "Additionally, CCL20 promotes ovarian cancer resistance by modulating ABCB1 expression and Notch1 signaling pathway." (PMID 40968783, 2026). "Therefore, targeting ABCB1 to overcome drug resistance in ovarian cancer represents a promising strategy." (PMID 41306963, 2025). "Furthermore, exosomes displaying tLyP-1 (exotLyP-1) effectively delivered ABCB1 siRNA into ovarian cancer cells, enhancing tumor cell drug sensitivity." (PMID 41306963, 2025). "Furthermore, NK92 cell-derived exosomes effectively delivered ABCB1 siRNA into recipient cells, mediating efficient gene silencing to sensitize chemoresistant ovarian cancer cells to therapeutic agents." (PMID 41306963, 2025).